EDN1 (endothelin 1)
Diseases named in the same sentence as EDN1 in open-access papers (continued):
Sharing a sentence is not in itself a finding about the gene and the disease.
chronic thromboembolic pulmonary hypertension (6 papers, 2016 to 2025). Chronic thromboembolic pulmonary hypertension (CTEPH) is characterized by the persistence of thromboemboli in the form of organized tissue obstructing the pulmonary arteries. "Endothelin-1 levels are raised in chronic thromboembolic pulmonary hypertension." (PMID 26874031, 2016). "Background and objectives: Endothelin-1 (ET-1) and transforming growth factor-β (TGF-β) play a pivotal role in the pathophysiology and vascular remodeling of chronic thromboembolic pulmonary hypertension (CTEPH) which is an under-diagnosed complication of acute pulmonary embolism (PE)." (PMID 39274190, 2024).
hyperthyroidism (6 papers, 2018 to 2025). Overactivity of the thyroid gland resulting in overproduction of thyroid hormone and increased metabolic rate. "This change was speculated to be caused by an increase in plasma endothelin-1, which was found to be positively correlated with FT3 levels in patients with hyperthyroidism." (PMID 40110675, 2025).
malaria (6 papers, 2008 to 2025). Malaria is a serious and sometimes fatal disease caused by a parasite that commonly infects a certain type of mosquito which feeds on humans. "Another vasoactive substance elevated in the plasma of malaria patients is endothelin-1 (ET-1)." (PMID 35514965, 2022).
osteoarthritis (6 papers, 2005 to 2025). A noninflammatory degenerative joint disease occurring chiefly in older persons, characterized by degeneration of the articular cartilage, hypertrophy of bone at the margins and changes in the synovial membrane. "For osteoarthritis treatment, functionalized nanogels incorporating endothelin-1 and bradykinin receptor antagonists have been designed to modulate inflammatory pathways and prevent cartilage degradation." (PMID 40286158, 2025). "Recently, a role for endothelin‐1 (ET‐1) has been proposed in osteoarthritis pathogenesis (Sin, Tang, Wen, Chung, & Chiu, 2015)." (PMID 28425564, 2017). "Additionally, chitosan/hyaluronic acid nanogels functionalized with endothelin-1 and bradykinin receptor antagonist peptides (BQ-123 and R-954) have been explored for osteoarthritis treatment, leveraging these peptides’ ability to modulate joint inflammation and pain signaling." (PMID 40286158, 2025). "The mechanism of endothelin-1 (ET-1)-induced nitric oxide (NO) production, MMP-1 production and MMP-13 production was investigated in human osteoarthritis chondrocytes." (PMID 15743480, 2005).
pancreatic cancer (6 papers, 1994 to 2025). "Treatment of mice xenografted with human pancreatic cancer with A platensis led to an underexpression of endothelin 1, pentraxin 3 and acidic fibroblast growth factor and an overexpression of 3 angiogenic proteins in tumours, including VEGF‐A and AREG acting via VEGFR or EGFR." (PMID 31957261, 2020).
polycystic ovary syndrome (6 papers, 2019 to 2023). A disorder that manifests as multiple cysts on the ovaries. "Stener-Victorin reported that repeated EA stimulation significantly promoted the release of β-endorphins in the hypothalamus of polycystic ovary (PCO) rats and reduced nerve growth factor (NGF), corticotropin-releasing factor (CRF), and endothelin-1 (ET-1) in the ovaries of PCO rats." (PMID 35832528, 2022).
Ascites (5 papers, 1996 to 2022). Accumulation of fluid in the peritoneal cavity (between the layers of the peritoneum that lines the abdomen). "Thus, we hypothesized expression differences of endothelin-1, TGF-β1, TGF-β2, and TGF-β3, of their receptors TβRI, TβRII, and of their pseudoreceptor BAMBI in lung tissue of broilers with ascites, with right cardiac failure but without ascites and in healthy broilers." (PMID 24286074, 2013).
brain infarct (5 papers, 2012 to 2025). "One method for producing a cerebral infarct in rodents is intracerebral injection of the vasoconstrictor peptide endothelin-1 (ET-1)." (PMID 22409811, 2012).
chondrosarcoma (5 papers, 2014 to 2024). A malignant cartilaginous matrix-producing mesenchymal neoplasm arising from the bone and soft tissue. "Endothelin-1 (ET-1), a potent vasoconstrictor, has been shown to enhance chondrosarcoma angiogenesis and metastasis." (PMID 27602960, 2016). "It has been shown that EDN1 mediates the activation of the PI3K/AKT pathway in lung fibrogenesis and in human chondrosarcoma cells." (PMID 24416389, 2014). "VEGF, FGF2, endothelin-1 (ET-1) and hypoxia-inducible factor-1α (HIF-1α) expression and mitogen activated protein kinase (MAPK) signaling are significantly enhanced in G2 and G3 conventional chondrosarcomas compared to G1 chondrosarcomas." (PMID 29361725, 2018).
cyst (5 papers, 2014 to 2025). A sac-like closed membranous structure that may be empty or contain fluid or amorphous material. "Endothelial alteration is favored by increased levels of endothelin-1 (a vasoconstrictor) in the cyst epithelium, cyst fluid, and plasma, along with reduced NO synthase activity, resulting in decreased NO production (a vasodilator)." (PMID 39200287, 2024). "Endothelin-1 (ET-1), an endothelium-derived vasoconstrictor and pro-fibrotic peptide, has emerged as a possible therapeutic target for inhibiting cyst growth and interstitial fibrosis in ADPKD." (PMID 26923419, 2016). "Immunohistochemically, stem cell factor and endothelin-1 were not expressed in the epithelial cells of the cyst wall." (PMID 24396444, 2014).
erectile dysfunction (5 papers, 2006 to 2026). Persistent or recurrent inability to achieve or to maintain an erection during sexual activity. "Membrane depolarization activates the NLRP3 inflammasome, with downregulation of endothelial Ca2+-activated K+ channels type 2.3 (KCa 2.3) and upregulation of endothelin-1 (ET-1) linked to erectile dysfunction." (PMID 41897372, 2026). "Endothelin-1–induced erectile dysfunction depends on Recombinant Staphylococcus aureus Exfoliative toxin A- and Recombinant Staphylococcus aureus Exfoliative toxin B-mediated activation of NLRP3 in mouse corpus cavernosum via Ca2+-dependent reactive oxygen species generation." (PMID 37636019, 2023).
fibromuscular dysplasia (5 papers, 2019 to 2025). A disorder characterized by fibrous thickening of the arterial wall resulting in narrowing of the arterial lumen. "Variants in the PHACTR1/EDN1 gene locus have been associated with vasculopathies including spontaneous coronary artery dissection (SCAD), fibromuscular dysplasia, and cervical artery dissection." (PMID 38259468, 2023).
focal segmental glomerulosclerosis (5 papers, 2016 to 2025). A renal disorder characterized by sclerotic lesions in the glomeruli. "It is well-established that focal segmental glomerulosclerosis (FSGS) arises from podocyte-endothelial crosstalk mediated by Edn1/Ednra-dependent mitochondrial dysfunction." (PMID 38374141, 2024). "Endothelin-1 (Edn1) was first identified as a downstream factor of transforming growth factor-β (TGF-β) in a model of focal segmental glomerulosclerosis (FSGS) and shown to induce albuminuria via mtROS in glomerular endothelial cells." (PMID 35327540, 2022).
Glomerular disease (5 papers, 2016 to 2024). "Y-27632 was previously identified to attenuates endothelin-1-induced glomerulopathy in the rats." (PMID 39455522, 2024).
hemorrhagic stroke (5 papers, 2010 to 2024). A stroke caused by a bleed on the brain. "SK3 immunoreactivity was then compared in the normal and damaged adult rat striatum, by injecting collagenase (a hemorrhagic stroke) or endothelin-1 (a transient ischemic stroke)." (PMID 20074365, 2010).
Impaired glucose tolerance (5 papers, 2014 to 2022). An abnormal resistance to glucose, i.e., a reduction in the ability to maintain glucose levels in the blood stream within normal limits following oral or intravenous administration of glucose. "Besides, other mechanisms such as impaired glucose tolerance, reduced nitric oxide, increased endothelin-1, and abnormal neuroendocrine signaling may be involved in arterial stiffness by AGEs." (PMID 35647076, 2022).
injury (5 papers, 2006 to 2023). Damage inflicted on the body as the direct or indirect result of an external force, with or without disruption of structural continuity. "Interestingly, some studies have found that endothelin-1 (ET-1) can also induce astrocyte activation after brain injury." (PMID 34867201, 2021). "The level of endothelin-1 (ET-1), a major mediator regulating both the vascular and the airway smooth muscle tone, has been reported to be elevated following the exposure of endothelial cells to hyperoxia, and also in different in vivo experimental models of acute lung injury." (PMID 16566828, 2006).
iron deficiency (5 papers, 2019 to 2025). "Regarding vascular function, magnesium deficiency decreases nitric oxide (NO) bioavailability, stimulates endothelin-1 secretion, and enhances vascular sensitivity to angiotensin II, consequently promoting vasoconstriction and elevated blood pressure." (PMID 41245414, 2025). "Iron deficiency directly exerted its effects on PASMCs by increasing the expression of the endogenous vasoconstrictor endothelin-1 (ET-1)." (PMID 31466321, 2019). "While retaining normal systemic iron levels, this model developed PAH and right heart failure as a consequence of intracellular iron deficiency and increased expression of the vasoconstrictor endothelin-1 (ET-1) within PASMCs." (PMID 31152133, 2019). "In a previous study of systemic iron deficiency, we had observed that endothelin-1 (ET-1) was markedly up-regulated in the lungs, including in the pulmonary arteries of mice fed an iron-deficient diet, and that this was prevented by administration of i.v. iron." (PMID 31152133, 2019).
metastatic prostate carcinoma (5 papers, 2008 to 2021). A carcinoma that arises from the prostate gland and has spread to other anatomic sites. "In 1995, Nelson and his colleagues showed significant elevation of immunoreactive endothelin-1 concentration in men with metastatic prostate cancer." (PMID 29515640, 2017). "In fact, the first clinical studies to specifically target osteoblasts in patients with metastatic prostate cancer was based on endothelin-1 (ET1), a mitogenic factor for osteoblasts that can promote the growth of osteoblasts at metastatic sites." (PMID 24069383, 2013). "Endothelin-1 is elevated in men with metastatic prostate cancer (PC), and can exert both an autocrine (epithelial) and a paracrine (stromal) influence on growth." (PMID 18781169, 2008). "Endothelin-1 is abnormally elevated in men with advanced metastatic prostate cancer (PC) and contributes to the transition to androgen independence." (PMID 18781169, 2008).
ocular hypertension (5 papers, 2013 to 2024). Abnormally high intraocular pressure. "Previous work has demonstrated that, similar to ocular hypertension, EDN1 injection was not sufficient to drive the death of amacrine cells." (PMID 35429992, 2022). "While EDN1 injection was shown to cause regional RGC and glial hypoxia (similar to glaucomatous ocular hypertension), oxygen deprivation itself is unlikely to cause this RGC death." (PMID 35429992, 2022).
optic neuritis (5 papers, 2016 to 2024). Optic neuritis is inflammation of the optic nerve, the nerve that carries the visual signal from the eye to the brain.The conditionmay cause sudden, reduced vision in the affected eye(s). "The hypoperfusion appears to be caused by raised concentrations of the potent vasoconstricting agent, endothelin-1, in the blood and cerebrospinal fluid in both optic neuritis and MS." (PMID 38474322, 2024). "The vasoconstriction can be attributed, at least in part, to increased plasma and cerebrospinal fluid concentrations of the potent vasoconstricting agent endothelin-1, which is well documented in both optic neuritis and MS." (PMID 38474322, 2024).
oral cancer (5 papers, 2020 to 2024). "Nociceptive mediators produced and secreted by oral cancer include, but are not limited to, nerve growth factor, ATP, endothelin-1 and other proteases." (PMID 34572924, 2021). "Endothelin-1 represents a potential biomarker for the development of OSCC in patients with oral lichen planus and IL-8, IL-1β, glycoprotein M2BP (Mac-2 binding protein), CD59, myeloid protein 14 (MRP14) and catalase as salivary biomarkers of oral cancer." (PMID 36412636, 2022).
retinal degeneration (5 papers, 2012 to 2021). Degeneration of the retina. "The retinal blood flow via the ophthalmic artery is regulated by EDN1 and over expression of EDN1 in endothelial cells cause progressive retinal degeneration." (PMID 27930693, 2016).
steatosis (5 papers, 2014 to 2025). Increased lipid within the cytoplasm of cells. "Liver-specific edn1 expression caused steatosis, fibrosis, glycogen accumulation, bile duct dilation, hyperplasia, and HCC in zebrafish." (PMID 24416389, 2014). "We also determined the expression levels of the mediators of the UPR pathway as this pathway is associated with the risk of steatosis, glycogen accumulation, and tumor formation, all these conditions being observed in the edn1 transgenic fish." (PMID 24416389, 2014). "Cumulatively, these results demonstrated that the liver-specific expression of edn1 causes up-regulation of several genes associated with lipid metabolism at 5 months of age, and these changes are consistent with the development of steatosis observed in the pathological analysis." (PMID 24416389, 2014). "Lu and colleagues have conducted liver up-regulated EDN1 expression in zebrafish, which leads to steatosis, fibrosis, and HCC." (PMID 34249676, 2021). "83% of EDN1 transgenic zebrafish shows steatosis by 5 months, 17‐18% of the fish developed hyperplasia by 7‐9 months, and 17‐20% of the fish exhibited HCC by 11mpf." (PMID 34766114, 2020). "All these genes were analyzed in the 5-month-old edn1 transgenic fish to verify the presence of steatosis at the molecular level." (PMID 24416389, 2014). "These pathological alterations reflect the gradual progression of HCC in the edn1 transgenic zebrafish, from steatosis to fibrosis, hyperplasia, and to HCC within 6 months (between 5 and 11 months of age)." (PMID 24416389, 2014). "Compared to the control zebrafish, which showed normal pathology at all stages, liver-specific edn1 expression significantly induced steatosis, bile duct dilation, and HCC (P<0.05)." (PMID 24416389, 2014). "However, 83% of the edn1 transgenic fish showed steatosis by 5 months, and approximately 30% of the fish still exhibited steatosis from 7 to 11 months." (PMID 24416389, 2014).
Airway obstruction (4 papers, 2007 to 2024). Obstruction of conducting airways of the lung. "EDN1 may act as a paracrine hormone causing sustained contraction of airway smooth muscle cells, accelerated growth of both fibroblasts and airway smooth muscle cells and increased oedema formation and mucus secretion, contributing to airway obstruction." (PMID 17470272, 2007).
amyotrophic lateral sclerosis (4 papers, 2021 to 2025). Amyotrophic lateral sclerosis (ALS) is a neurodegenerative disease characterized by progressive muscular paralysis reflecting degeneration of motor neurons in the primary motor cortex, corticospinal tracts, brainstem and spinal cord. "Endothelin-1 (ET-1), a secreted signaling peptide, is suggested to be involved in multiple actions in various tissues including the brain, but its role in amyotrophic lateral sclerosis (ALS) remains unknown." (PMID 36531135, 2022).
aneurysm (4 papers, 2021 to 2023). Bulging or ballooning in an area of an artery secondary to arterial wall weakening. "A study reported the size of abdominal AA to be associated with concentration of D-dimer, while another study suggested endothelin-1 (ET-1), which is released from endothelial cells in response to among other factors vascular injury, as a marker of aneurysm diameter." (PMID 36817421, 2023).
Arterial dissection (4 papers, 2021 to 2024). A separation (dissection) of the layers of an artery. "Edn1 (Endothelin 1) genetic locus is correlated to spontaneous coronary artery dissection." (PMID 34130651, 2021).
Arthritis (4 papers, 2011 to 2022). Inflammation of a joint. "In fact, budlein A ameliorates murine antigen-induced arthritis by inhibiting NF-κB activation and thereby Il-33, Tnf-α, Il-1β, endothelin-1, and Cox-2 mRNA expression in the knee joint." (PMID 30319413, 2018). "Our genome-wide microarray analysis revealed that endothelin-1 (ET-1) and endothelin-2 (ET-2) showed a marked up-regulation in dorsal root ganglia during the acute phase of arthritis." (PMID 21689431, 2011).
atopic dermatitis (4 papers, 2020 to 2025). "In pathological states, these cells display modified gene expression patterns and secrete inflammatory cytokines, such as thymic stromal lymphopoietin (TSLP) and endothelin‐1 (ET‐1), contributing to skin ailments like eczema and atopic dermatitis." (PMID 41388848, 2025). "Other cells responsible for itching and pain in atopic dermatitis include keratinocytes, which secrete TSLP, and endothelin-1 (ET-1) and NGF, which are factors that activate nerves and lead to increased sensitivity and dysfunction of the skin barrier." (PMID 38672221, 2024).
Autoimmunity (4 papers, 2019 to 2025). The occurrence of an immune reaction against the organism's own cells or tissues. "The pathogenesis of PAH in connective tissue diseases, including RA, encompasses traditional pathways associated with endothelin-1, nitric oxide, and prostacycline, alongside inflammation and autoimmunity." (PMID 40620598, 2025). "Unlike the idiopathic form, inflammation and autoimmunity are believed to contribute to the initiation and progression of CTD-PAH via endothelin 1, nitric oxide, and prostacyclin pathways." (PMID 40138866, 2025).
bladder cancer (4 papers, 2013 to 2020). "In models of bladder cancer metastasis to the lung, it has been demonstrated that DTC-derived endothelin-1 (ET-1) and ETAR activity are necessary conditions for successful lung metastatic colonization, demonstrating not just immune modulation but also secretory support ensures from these cells." (PMID 33022920, 2020). "By acting on endothelin-1 (ET-1) receptor, tumor-derived ET-1 induced the migration of both tumor cells and macrophages into lungs and also induced the expression of pro-inflammatory cytokines including IL-6 and CCL2 in several bladder cancer lung metastasis models." (PMID 30597969, 2018).
bronchopulmonary dysplasia (4 papers, 2018 to 2022). Bronchopulmonary dysplasia is a chronic respiratory disease that results from complications related to lung injury during the treatment of infant acute respiratory distress syndrome in low-birth-weight premature infants or from abnormal lung development in older infants. "For example, the extrinsic coagulation pathway together with C5a can promote fibrosis in bronchopulmonary dysplasia (a serious pulmonary fibrotic disorder) via the endothelin-1 signaling pathway." (PMID 33953300, 2021).
chronic lung disease (4 papers, 2020 to 2025). According to the definitions of the American and British Thoracic Societies, including pulmonary functional tests, X-rays, and CT scans for items such as fibrosis, bronchiectasis, bullae, emphysema, nodular or lymphomatous abnormalities. "Endothelin-1 (ET-1) receptor antagonists offer a promising field of research in preterm chronic lung disease." (PMID 35123510, 2022). "In summary, we have explored the crucial roles of angiogenesis and immunity in the onset and progression of ILD and COPD, and we identified COL10A1, EDN1, MMP1, and RRAS as potential novel therapeutic targets for chronic lung diseases." (PMID 40002743, 2025).
complication (4 papers, 2017 to 2024). Any disease or disorder that occurs during the course of, or because of, another disease, treatment, or procedure. "PKC is a regulator of smooth muscle contraction within the tunica media of arteries and can be induced by endothelin-1 (ET-1), which is also implicated in diabetic vascular complications." (PMID 36634048, 2023).